IL2 (interleukin 2)
Diseases named in the same sentence as IL2 in open-access papers (continued):
Sharing a sentence is not in itself a finding about the gene and the disease.
cancer (continued). "Additional GSs putatively involved in cancer were those implied in cell cycle regulation (“E2F targets”, “G2M checkpoint”) and cell proliferation (“IL2 STAT5 signaling”, “mTORC1 signaling”)." (PMID 32610656, 2020). "On the basis of this knowledge, many studies found diverse types of cancer to be sensitive towards a cytokine therapy and confirmed the positive impact of IL-2 with regard to immuno-therapeutical cancer therapy." (PMID 33027905, 2020). "IL-15 has emerged as an alternative to IL-2 in cancer treatment, for its potent effects on cytolytic NK and T cells without inducing suppressive Treg cells." (PMID 33266177, 2020). "The antitumor effect of IL-2 resulting from its capacity to expand and activate effector lymphocytes in vivo has been translated into the first available cancer immunotherapy." (PMID 33266177, 2020). "Of practical relevance for cancer treatment, it also significantly diminished the efficacy of the IL-2/doxorubicin chemo-immunotherapy treatment regimen and substantially, yet not significantly, aggravated the effects of the anti-PD-L1 treatment." (PMID 33344239, 2020). "T cells mediate the response to PD-1 and CTLA-4 CPI therapy, as well as adoptive chimeric antigen receptor (CAR) T-cell therapy and cancer vaccines, positioning T-cell growth factors such as IL-2 as ideal combination partners." (PMID 32005826, 2020). "While the reasons for occasional remissions in IL-2-treated cancer patients remained unclear, further investigations continued to clarify its mode of action." (PMID 32917054, 2020). "Discerning the roles of IL-2 and IL-15 in the regulation of antitumor immune responses is critical for the development of immunotherapeutic approaches against cancer." (PMID 33266177, 2020). "When γδT cells are expanded in vitro in the presence of IL‐2 and a synthetic agonist, or IL‐15 123, 124, 125 they exhibit powerful killing of human cancer cells and cell lines." (PMID 32480431, 2020). "Immune checkpoint blockade (e.g., anti-PD1/PD-L1), adoptive cell transfer (e.g., CAR T), cancer vaccines (e.g., Sipuleucel-T) and immunostimulatory cytokines (e.g., IL-2) are the principal immunotherapeutic tools." (PMID 32823961, 2020). "The history of the use of cytokines as agents for the treatment of various diseases, including cancer, began in the mid-1990s when the anticancer effect of High-dose (HD) IL2 therapy was first demonstrated." (PMID 32582698, 2020). "The administration of interleukin-2 (IL-2) and the adoptive transfer of antitumor T cells grown in IL-2 represented the first effective immunotherapies for cancer in humans." (PMID 32455666, 2020). "The use of IL-2 to activate the immune system of cancer patients was an early milestone in current cancer immunotherapy." (PMID 33247183, 2020). "High-dose IL-2 treatment was the first FDA-approved immunotherapy for cancer, while low-dose IL-2 administration has shown promise in allograft rejection and autoimmune and inflammatory diseases." (PMID 32917054, 2020). "Reasons that prevent the extensive usage of IL2 for cancer therapy include short half-life in vivo, severe toxicity at therapeutic dosage, and propensity to promote Treg proliferation." (PMID 33381115, 2020). "It participates in various pathways, including inducible costimulator (iCOS)-iCOS ligand signalling in T-helper cells, IL-2 signalling and the PD-1/PD-L1 cancer immunotherapy pathway." (PMID 32616892, 2020). "They reported that long-term culture of CAR T cells with IL-2 promotes their terminal differentiation however, their short-term culture with IL-2 increases the generation of memory CAR T cells which are desirable subsets in CAR T cell cancer therapy." (PMID 32391013, 2020). "Immunotherapy, which started with IL-2 and interferon-alpha in the late 1980s, later increased with the use of ICIs and has become one of the main elements of cancer treatment today." (PMID 32512674, 2020).
cancer (continued). "IL-2 is essential for NK cell lytic activity and activation of T cytolytic cells, which participate in killing of viruses, bacteria, and cancer cells." (PMID 32411807, 2020). "Immunotherapy has improved the treatment outcomes in patients with cancer, and continuous efforts are devoted to exploiting the therapeutic potential of IL-2 and IL-15 based on their ability to expand and activate cytolytic lymphocytes in vivo." (PMID 33266177, 2020). "The overall physiological role for IL-2 is to meticulously co-ordinate the Th1-type immune response against certain pathogens and cancers." (PMID 32326210, 2020). "Interleukin-2 (IL-2) is a component of most protocols of adoptive cell transfer (ACT) therapy for cancer, but is limited by short exposure and high toxicities." (PMID 32005809, 2020). "Another illustration of an agent developed at a high dose for cancer treatment which was subsequently pursued at a low dose for immune-mediated diseases is the cytokine interleukin-2 (IL-2)." (PMID 32733473, 2020). "IL-2 was used as the first reproducible effective human cancer immunotherapies due to its ability to expand T cells with maintenance of functional activity." (PMID 32742470, 2020). "The enriched cancer hallmarks in low-risk group, including the interferon alpha (IFN-α) response, the interferon-γ (IFN-γ) response, IL-2/STAT5 signaling, IL-6/JAK/STAT3 signaling, epithelial mesenchymal transition, TGF-β signaling and hedgehog signaling." (PMID 32850356, 2020). "On the other hand, in infected cardiomyocytes, there are more genes related to cell cycle signaling, interleukin-2 signaling, cancer-related pathways, T cell receptor regulation of apoptosis, and hemostasis pathway." (PMID 33233425, 2020). "A high amount of fibroblasts was also associated with a higher infiltration of anti-cancer immune cells, such as CD8+ T-cells and dendritic cells, together with higher inflammatory signaling, including IL2/STAT5 and IL6/JAK/STAT3 signaling." (PMID 32485981, 2020). "The phosphorylation of signaling proteins downstream of IL-2/12 receptors was assessed using two 7 color flow cytometry panels in 13 healthy donors and nine cancer patients." (PMID 32508837, 2020). "Pegylated forms of IL2 have shown superior properties in mouse models of cancer and encouraging results in patients as single agents or in combination with anti-PD-1 antibodies." (PMID 33110477, 2020). "IL-2 is one of the key cytokines with pleiotropic effects on the immune system and it was an early candidate for cancer immunotherapy, approved for the treatment of metastatic renal cell carcinoma (1992) and later for metastatic melanoma (1998) by FDA." (PMID 32423420, 2020). "Emerging knowledge of the two type I cytokine family members IL-2 and IL-15 has led to critical therapeutic implications for cancer treatment." (PMID 33266177, 2020). "We have also previously shown that MBZ induces an M1 phenotype in human macrophage models and potentiates the anti-cancer activity of CD3/IL-2 activated peripheral blood mononuclear cells (PBMCs), the effect being attenuated by removal of CD14+ myeloid cells." (PMID 32753665, 2020). "In particular, statins plus IL-2 increased IL-1β and IL-18 production in CD56+ DC/macrophage-like cells, which in turn cooperate with IL-2 to induce IFNγ release by NK cells, dampening cancer progression." (PMID 32823961, 2020). "In the secretome of patients with advanced carcinoma, it has been possible to find a positive correlation between the secretion of IL-6, IL-1β, IL-2, and IL-4 and the concentration of MGAs." (PMID 32630302, 2020). "High-dose IL-2 is one of the first immunotherapeutic drugs to demonstrate initial clinical efficacy in advanced cancer patients." (PMID 31998135, 2019). "When the T helper lymphocyte recognizes the antigen, it produces cytokines such as interleukin-2 (IL-2) that stimulate B lymphocytes to produce antibodies (humoral immunity) and stimulate cytotoxic T lymphocytes to kill cancer cells." (PMID 31766386, 2019).
cancer (continued). "Neutrophils secrete a variety of cytokines such as interleukin-2, interleukin-10, which is beneficial to cancer progression." (PMID 31921649, 2019). "When compared with the untreated mice, the anti-cancer-related cytokines, IL-2 and IFNγ, occurred at a higher level in the serum of CH-treated mice, whereas the amounts were not significantly (p < 0.05) higher in the CL-treated mice." (PMID 30814922, 2019). "NKF-NK cells exhibited markedly increased cytotoxic activity against a wide variety of cancer cell lines as compared to IL-2-NK cells." (PMID 31624330, 2019). "In particular, the anti-cancer effects of IL-18 accompanied by the activation of NK cells and T cells are often manifested in high doses of IL-18 in combination with IL-2 or IL-12." (PMID 31731729, 2019). "Given the ability of IL-2 to expand CD8 T cells and to maintain their cytotoxic function, infusion of recombinant IL-2 in cancer patients was the first reported effective immunotherapy for human cancer." (PMID 31766350, 2019). "Interleukin-2 (200 IU/mL) and IL-21 (20 ng/mL) were tested, as these cytokines are known to bear the highest potential for the generation of anti-cancer immune effector cells." (PMID 31336622, 2019). "Interferon-α and interleukin-2 have also been investigated as candidate genes for cancer immune-gene-therapy." (PMID 31430949, 2019). "While IL-2 can potently activate both NK and T cells, its short in vivo half-life, severe toxicity, and propensity to amplify Treg cells are major barriers that prevent IL-2 from being widely used for cancer therapy." (PMID 31462678, 2019). "The three largest groups of IL-2-driven genes in the thymus were related to cancer, Jak/STAT, and T cell signaling, consistent with developmental progression of Tregs." (PMID 30833563, 2019). "T cells grown ex vivo using IL-2 represented the first efficacious T cell product for cancer immunotherapy." (PMID 31195686, 2019). "The ability of IL-2 to expand T cells with maintenance of functional activity has been translated into the first reproducible effective human cancer immunotherapies." (PMID 31703694, 2019). "These antitumor roles of CD4+ Th1 cells are mainly driven by the triad of cytokines, such as IFN-γ, TNF-α and IL-2.5,6 Furthermore, a clinical benefit associated with Th1-polarised signature in the TME has been reported in many human cancers." (PMID 31358938, 2019). "Cytokines such as interferon alpha (IFN-α) and interleukin 2 (IL-2) are administered to cancer patients as an immunomodulatory agent to promote various anticancer activities." (PMID 31731818, 2019). "Due to its ability to enhance T cell as far as NK cell proliferation, homeostasis and cytotoxicity, IL-2 was the first cytokine employed in the clinic to boost immune responses in cancer patients." (PMID 30939820, 2019). "JAWS II DC were capable of activating the CD4+ T cells to produce significant levels of IL-2 when co-cultured with SMG E.G7 cancer cells as compared to co-culture with Static E.G7." (PMID 31602007, 2019). "The clinical efficacy of immunomodulatory cytokines, mostly IFN- α and IL-2, was studied for various cancers types." (PMID 31731818, 2019). "High dose IL-2 is administered to cancer patients to support the proliferation and function of cytotoxic T lymphocytes (CTLs)." (PMID 30842774, 2019). "On the other end, IL2 is able to promote a selective boosting of T cell and NK cell activity against cancer cells." (PMID 31799191, 2019). "There has been substantial interest in exploring the use of IL2 in cancer immunotherapies, which have been hampered by side effects including the expansion of Tregs." (PMID 31595191, 2019). "Pro-inflammatory cytokines IL-2, IL-12 and IFN-γ are associated with good prognosis in cancer, whilst an increase of immunosuppressive cytokines IL-6, IL-10 and TGF-β correlates to poor outcome." (PMID 30232514, 2019).
cancer (continued). "Interleukin-2 (IL-2) based cancer therapy is limited by severe toxicity and strong Treg amplification at the therapeutic dosage." (PMID 31462678, 2019). "Interleukin 2 (IL-2) has been used for the treatment of different types of cancer that express the IL-2 receptor (IL-2R)." (PMID 31662754, 2019). "Preclinical experiments with several murine cancer models showed very promising antitumor effects of granulocyte–macrophage colony-stimulating factor (GM-CSF), IL-2, IL-12, IL-15, and IL-21." (PMID 31083515, 2019). "The importance of targeting IL-2 to transferred T cells has also shown promise in the field of cancer immunotherapy." (PMID 30842774, 2019). "Whereas IFNγ and TNF are canonical pro-inflammatory cytokines, IL-2 has attained a more dichotomous role in cancer immunotherapy, with T cell stimulatory capacities on one hand and immunosuppressive characteristics on the other hand." (PMID 31195686, 2019). "Sufficient (or “functional”) concentrations of IL-2, IL-12 and IFN-γ were positively associated with prognosis in cancer." (PMID 30232514, 2019). "Though administration of IL-2 has been reported to promote systemic inflammation and febrile illness in cancer patients, detailed analysis of how IL-2 impacts the lung environment is lacking." (PMID 31412088, 2019). "During the same period another immunotherapy agent, the natural cytokine molecule interleukin-2 (IL-2), emerged as a promising anti-cancer agent and its recombinant form aldesleukin won FDA approval for treating metastatic renal cancer in 1992." (PMID 31624532, 2019). "IL-2 alone or in combination with other anti-cancer therapies have brought some survival benefits to advanced cancer patients." (PMID 29980186, 2018). "The use of immunostimulatory drugs can induce unexpected changes in VEGF levels, as we observed an increase in VEGF serum levels following treatment with ZOL plus low-dose IL-2 in cancer patients." (PMID 29725332, 2018). "T cell exhaustion has been described in cancer and is a state in which T cells are unable to proliferate, produce lower levels of cytokines such as IL-2 and IFN-γ, have diminished cytotoxic activity and effector function, and cannot generate memory responses." (PMID 30560130, 2018). "Further, genetic modification of T cells with αβ TCRs or chimeric Ag receptors encoding gene and administration of these cells after expansion in IL-2 have opened the scope for use of cell transfer therapy in other cancer types." (PMID 29854806, 2018). "IL-2 has been widely used in cancer immunotherapy for both stimulation of autologous NK cells and activation/expansion of donor NK cells." (PMID 29713323, 2018). "In agreement with the existing evidence, treating whole blood of patients with cancer with IL-2, IL-15 and IL-21 markedly improved the antigen-specific IFNγ response regardless of existing immunosuppression, thereby suggesting clinical applicability." (PMID 29970101, 2018). "Our data suggest that vvDD-IL-2-RG as a new form of IL-2 immunotherapy can reverse the cancer-immune set point and represent a treatment for cancers, which are to date unresponsive to immunotherapy." (PMID 30410056, 2018). "Cytokines, such as IL-2 have played a pivotal role in the war against multiple types of cancer, however, the clinical applications are limited due to the severe toxicities associated with high doses delivered systemically." (PMID 30410056, 2018). "Low-doses of IL-2 lead to the preferential expansion of Treg cells; this is an unwanted effect in anti-cancer immunotherapy." (PMID 30619269, 2018). "This review discusses scope of IL-2 in the immunotherapy of cancer and major challenge in the development of IL-2 based therapeutic approach as well as perspective on future research." (PMID 29854806, 2018). "NDV expressing human IL-2 was generated and demonstrated to express IL-2 upon infection of various human cancer cell line." (PMID 29857493, 2018).
cancer (continued). "For the experiments, we used IL-2 activated NK cells to resemble the clinical situation where ex vivo (IL-2) activated NK cells will be infused into cancer patients." (PMID 29500635, 2018). "A variety of cytokines have been approved as drugs for the treatment of cancer patients, including IL-2, IFN-γ, and GM-CSF." (PMID 29896199, 2018). "Two groups have reported that in cancer patients the number of Tregs increased after IL-2 treatment." (PMID 30250191, 2018). "IL-2 has been part of cancer treatment for many decades and is considered the first immunotherapy proven to be effective in human cancer in 1984." (PMID 29544515, 2018). "In the context of cancer immunotherapy, the effect of CQ has been evaluated in combination with high-dose interleukin-2 (HDIL-2) in preclinical murine hepatic metastasis model." (PMID 29922284, 2018). "IL-2 is established as an effective treatment for several types of cancer for about 30 years and N-BPs are widely used for osteoporosis, hypercalcemia, and the treatment of bone metastasis." (PMID 29725332, 2018). "Recombinant IL-2 has been approved for the treatment of cancers (malignant melanoma, renal cell cancer) and has been tested in clinical trials for the treatment of chronic viral infections, and as an adjuvant for vaccines." (PMID 30257675, 2018). "IL-2 plays a critical role in regulating T cell responses, making it an attractive target to treat autoimmune diseases and cancer." (PMID 30319612, 2018). "IL-2-immunocytokines in preclinical and clinical development for treatment of various types of cancer." (PMID 30619269, 2018). "Sufficient NK cells to perform both the priming and IL-2 stimulation assays were only obtained from 21 of 24 patients (5 benign, 16 cancer)." (PMID 30761160, 2018). "On the other hand, cancer septic animals exhibit a decrease in a subset of PD-1lo 2B4lo IL-2-secreting CD4+ T cells (i.e. Nodes 3 and 4) relative to previously healthy septic controls." (PMID 29338031, 2018). "The IL-2 administration is reported to induce apparently curative and durable regressions in cancer patients." (PMID 29854806, 2018). "IL-2 has been reported to induce complete and durable regressions in cancer patients but immune related adverse effects have been reported (irAE)." (PMID 29854806, 2018). "The addition of a high concentration of exogenous ADO did not lead to a significant reduction in cytolysis against A549 cancer cells by cytokine-stimulated NK cells when primed with either IL-2 or a combination of IL-12 and IL-15." (PMID 30425720, 2018). "IFN-γ is important in the immune system stems for its immunomodulatory activity, whereas IL-2 can promote the differentiation of T cells into effector T cells and boost the host immunity against cancer." (PMID 30109250, 2018). "TG4010 is a therapeutic cancer vaccine based on a modified vaccinia Ankara strain (MVA) encoding for the full-length cancer antigen Mucin 1 (MUC1) and human IL-2." (PMID 28923084, 2017). "IL-2, as a passive cancer immunotherapy agent, has attracted attention by exhibiting some antitumor activities both as a single agent and as a complement to other therapeutic approaches." (PMID 27805072, 2017). "The most validated cytokines involved in cancer progression are IL-1, IL-4, IL-6, while IL-2 has been the most understood anti-inflammatory cytokines used to boost the host immunity against cancer." (PMID 28927416, 2017). "At the same time, the transwell coculture of cancer cells and Jurkat T cells also inhibited the secretion of IL-2 at lower levels." (PMID 28404966, 2017). "Advanced research using bifunctional fusion protein of melittin and interleukin-2 (melittin-IL-2) showed an increased cytotoxicity in human liver (SMMC-7721 cancer cells), lung (A549 cancer cells), and ovarian (SKOV3 cancer cells) cancer xenograft models." (PMID 29246030, 2017).